CCT8 (chaperonin containing TCP1 subunit 8)
Description:
Component of the chaperonin-containing T-complex (TRiC), a molecular chaperone complex that assists the folding of actin, tubulin and other proteins upon ATP hydrolysis. The TRiC complex mediates the folding of WRAP53/TCAB1, thereby regulating telomere maintenance. As part of the TRiC complex may play a role in the assembly of BBSome, a complex involved in ciliogenesis regulating transports vesicles to the cilia.
Synonyms: C21orf112; CCTQ; PRED71; D21S246
Tractability: Small molecule: a structure with a bound ligand is known. Antibody: its Gene Ontology location is reachable by antibodies, with high confidence. PROTAC: UniProt records ubiquitination sites on it; ubiquitination databases record sites on it; its protein half-life has been measured.
Gene: Protein-coding gene on chromosome 21 (29,055,805 to 29,073,797, reverse strand). Ensembl gene ENSG00000156261.
Subcellular location: Cytoplasm; Cytoplasm, cytoskeleton, microtubule organizing center, centrosome; Cytoplasm, cytoskeleton, cilium basal body
Subcellular location (Human Protein Atlas): Connecting piece; End piece; Nucleoplasm; Cytosol; Mid piece; Principal piece
Pathways (Reactome):
Metabolism of proteins: Association of TriC/CCT with target proteins during biosynthesis; Cooperation of PDCL (PhLP1) and TRiC/CCT in G-protein beta folding; Folding of actin by CCT/TriC; Formation of tubulin folding intermediates by CCT/TriC; Prefoldin mediated transfer of substrate to CCT/TriC
Immune System: Neutrophil degranulation
Organelle biogenesis and maintenance: BBSome-mediated cargo-targeting to cilium
Gene Ontology:
Molecular function: cadherin binding; protein binding; protein folding chaperone; ATP binding; ATP hydrolysis activity; ATP-dependent protein folding chaperone
Biological process: positive regulation of protein localization to Cajal body; positive regulation of telomerase RNA localization to Cajal body; positive regulation of telomere maintenance via telomerase; protein folding; protein stabilization
Cellular component: centrosome; chaperonin-containing T-complex; cytoplasm; cytosol; extracellular exosome; microtubule; azurophil granule lumen; extracellular region; ficolin-1-rich granule lumen; secretory granule lumen; cell body; zona pellucida receptor complex
Genetic constraint (gnomAD): Loss-of-function variants: 7 observed, 45.77 expected, observed/expected ratio (o/e) 0.15, 90% interval 0.086 to 0.29. The upper end of that interval is the gene's LOEUF score, 0.29, which puts it in group 1 of 6, group 1 being the genes least tolerant of losing a copy. Missense variants: 456 observed, 526.48 expected, observed/expected ratio (o/e) 0.87, 90% interval 0.8 to 0.94. Synonymous variants: 164 observed, 174.24 expected, observed/expected ratio (o/e) 0.94, 90% interval 0.83 to 1.07.
Homologues: Orthologues: chimpanzee CCT8 (99% identical), macaque CCT8 (98% identical), mouse Cct8 (97% identical), rat Cct8 (97% identical), guinea pig CCT8 (97% identical), pig CCT8 (96% identical), dog CCT8 (96% identical), rabbit CCT8 (96% identical), tropical clawed frog cct8 (87% identical), zebrafish cct8 (84% identical), Drosophila melanogaster CCT8 (61% identical), Caenorhabditis elegans cct-8 (57% identical). Paralogues in human: CCT8L2 (32% identical), TCP1 (29% identical), CCT5 (28% identical), CCT3 (27% identical), CCT4 (27% identical), CCT7 (26% identical), CCT6A (25% identical), CCT2 (25% identical), PIKFYVE (24% identical), CCT6B (24% identical), HSPD1 (19% identical), MKKS (17% identical), and 1 more.
Diseases named in the same sentence as CCT8 in open-access papers:
CCT8 is named in the same sentence as 30 diseases in open-access papers, as found by Europe PMC text mining. Sharing a sentence is not in itself a finding about the gene and the disease. The quoted sentences say what the papers report.
hepatocellular carcinoma (11 papers, 2016 to 2025). A malignant tumor that arises from hepatocytes. "CCT8 plays a key role in various cancers such as non-Hodgkin's lymphoma, glioma, colon cancer, and hepatocellular carcinoma." (PMID 41203126, 2025). "For example, there is a significant difference in the expression of TCP1/CCT2/CCT3/CCT4/CCT5/CCT6A/CCT7/CCT8 in hepatocellular carcinoma." (PMID 37058032, 2023). "Studies have shown that CCT8 can promote the proliferation and invasion of hepatocellular carcinoma, esophageal squamous cell carcinoma, and glioma cells." (PMID 34862361, 2021). "In various cancers, the expression levels of different CCT subunits were upregulated in varying degrees: CCT3 in hepatocellular carcinoma, and CCT8 in hepatocellular carcinoma and glioblastoma." (PMID 33869000, 2021). "In addition, studies have also shown that CCT8 is overexpressed in colon cancer and hepatocellular carcinoma." (PMID 34862361, 2021). "For example, CCT3 and CCT8 were overexpressed in hepatocellular carcinoma (HCC) and the proteins were detected in the plasma from patients, suggesting that CCT3 could be used as a biomarker for screening HCC." (PMID 29299146, 2017). "Previous studies reported that the expression levels of different CCT subunits were upregulated in various cancers, such as CCT2 in prostate, breast, and lung cancers, CCT3 in hepatocellular carcinoma (HCC), and CCT8 in HCC and glioblastoma." (PMID 33815471, 2021). "Other reports indicated that knocking down CCT8 significantly reduced CDK2 levels in hepatocellular carcinoma (HCC), suggesting substrate specificity variations among CCT subunits, the reasons for which remain unclear and warrant further investigation." (PMID 39928781, 2025). "For instance, CCT8 regulates cell proliferation, migration and invasion in several tumors; CCT2 inhibition reduces cell migration in tubulin-binding agent-resistant tumors; and CCT3 supports cell proliferation in hepatocellular carcinoma." (PMID 33917510, 2021).
glioma (10 papers, 2016 to 2025). A benign or malignant brain and spinal cord tumor that arises from glial cells (astrocytes, oligodendrocytes, ependymal cells). "As well, change in expression of CCT8 has been linked to poor prognosis in glioma patients." (PMID 31270132, 2019). "Numerous studies have demonstrated that CCT8 plays a significant role in tumor progression in B-cell non-Hodgkin's lymphoma and glioma." (PMID 39717265, 2024). "Many studies have shown that CCT, especially subunit 8 (CCT8), plays an important role in the tumor progression of B cell non-Hodgkin’s lymphoma and glioma." (PMID 34862361, 2021). "Silencing CCT8 also inhibited the proliferation and invasion capacities of glioma cells and dysregulated cytoskeletal dynamics." (PMID 34676169, 2021). "Compared with the controls, the glioma cells expressing CCT8-siRNA exhibited a significantly decreased proliferation and invasion capacity." (PMID 33815471, 2021). "This is consistent with the reduction in cell migration and invasion observed in glioma cells following siRNA-mediated knockdown of CCT8." (PMID 30578123, 2019). "Moreover, analyses of gene expression and DNA copy number showed that CCT2, CCT3, CCT5, CCT6A, and CCT7 are upregulated in GBM compared with normal brain tissue, while CCT2, CCT3, CCT5, CCT6A, and CCT8 display higher copy numbers than in low-grade gliomas." (PMID 41516249, 2025). "Similarly, the CCT8 subunit exhibits elevated expression in gliomas, and its knockdown results in reduced cell proliferation, angiogenesis, migration, and invasion." (PMID 41516249, 2025).
colorectal cancer (6 papers, 2021 to 2025). A primary or metastatic malignant neoplasm that affects the colon or rectum. "As an important subunit of the CCT complex, studies have shown that CCT8 is associated with the progression of colorectal cancer, breast cancer, lung cancer, and uterine sarcoma." (PMID 34862361, 2021). "In order to further explore the possible mechanism of CCT8 in colorectal cancer, bioinformatics techniques were used to enrich and analyze the regulatory molecules or signal pathways downstream of CCT8." (PMID 34862361, 2021). "The results showed that the overall survival rate of colorectal cancer patients with high expression of CCT8 was significantly lower than that of patients with low expression of CCT8 (P = 0.0425)." (PMID 34862361, 2021). "Given that TALIN-1, MRE11, and CCT8 interact with E-cadherin, that FASN, FLNA, and DDX3X are implicated in EMT, and that FKBP4 expression is upregulated in colon cancers, we examined E-cadherin expression in human colorectal carcinoma HCT116 cells under the FKBP4 knockdown." (PMID 41203126, 2025). "CCT8 could prevent the cell cycle arrest in colorectal cancer." (PMID 37500615, 2023). "Therefore, silencing the types of CRC with overexpression of CCT8 may be a promising method for the treatment of recurrence and metastasis of colorectal cancer." (PMID 34862361, 2021). "Our results showed that LASP1 can bind to CCT8, and CCT8 can restore the ability of LASP1 to promote the invasion of colorectal cancer cells." (PMID 34862361, 2021). "However, the mechanism of CCT8 in the occurrence and development of colorectal cancer is not clear." (PMID 34862361, 2021).
esophageal squamous cell carcinoma (5 papers, 2021 to 2024). Esophageal squamous cell carcinoma (ESCC) is a type of esophageal carcinoma (EC) that can affect any part of the esophagus, but is usually located in the upper or middle third. "Knockdown of CCT8 in esophageal squamous cell carcinoma (ESCC) cells downregulated actin and tubulin and enhanced cell death upon treatment with cisplatin." (PMID 35602608, 2022). "Furthermore, it was reported that knockdown of CCT8 expression enhanced the inhibitory effects of cisplatin on esophageal squamous cell carcinoma TE-1 cells." (PMID 34612768, 2021).
breast carcinoma (4 papers, 2021 to 2023). "Blocking the activation of AKT by MK2206, a phase II inhibitor of AKT for breast cancer patients, rescued E-cadherin expression and suppressed CCT8-induced cell-scattered growth, cell migration, cell mobility and tumor metastasis." (PMID 37928427, 2023).
glioblastoma (4 papers, 2021 to 2022). The most malignant astrocytic tumor (WHO grade IV). "CCT8 depletion in glioblastoma multiforme (GBM) cells affected the cytoskeleton and decreased proliferation and invasion, which was also observed in HCC cell lines." (PMID 35602608, 2022).
lung carcinoma (3 papers, 2021 to 2023). "Since our research interest is lung cancer, we then investigated the association of CCT8 mRNA expression with the overall survival of lung cancer." (PMID 37928427, 2023). "CCT8 expression in two subtypes of lung cancer results in different clinical outcomes; higher expression of CCT8 is associated with poor survival in LUAD patients, while higher expression of CCT8 is good for LUSC patients." (PMID 37928427, 2023). "Given that CCT8 mRNA expression increased obviously in both LUAD and LUSC, the main subtypes of lung cancer, we further analyzed the association of CCT8 expression with the outcome in LUAD and LUSC." (PMID 37928427, 2023). "The aims of the present study were to examine the expression of CCT8 and evaluate its prognostic significance in lung cancer." (PMID 37928427, 2023). "In conclusion, we found that the expression of CCT8 is frequently increased in human lung cancer." (PMID 37928427, 2023). "In this study, we demonstrated that CCT8 expression is frequently increased in human lung cancer." (PMID 37928427, 2023). "However, little is known about the expression and prognostic significance of CCT8 (subunit 8 of the CCT complex chaperonin) in lung cancer." (PMID 37928427, 2023). "In this study, we symmetrically analyzed the mRNA expression of CCT8 by TIMER 2 on the basis of the TCGA dataset and found that CCT8 mRNA is higher in both LUAD and LUSC, the two main subtypes of lung cancer, than in normal specimens." (PMID 37928427, 2023). "However, the expression and prognostic significance of CCT8 in lung cancer is not clear." (PMID 37928427, 2023).
pancreatic cancer (3 papers, 2019 to 2024). "CCT8 is also recognized as a potential biomarker for invasion and metastasis in colorectal, hepatocellular, and pancreatic cancers." (PMID 39717265, 2024). "According to the literature, with the exception of CCT8, the other three proteins can be detected in blood samples of pancreatic cancer patients, and they can be used as prognostic markers." (PMID 31632196, 2019). "To investigate the potential role of CCT8 in the metastasis of pancreatic cancer, we knocked down the expression of CCT8 in PC-1.0 and AsPC-1 cell lines." (PMID 31632196, 2019). "Further in vitro functional experiments showed that knockdown of CCT8 suppressed invasion and metastasis of pancreatic cancer cell lines." (PMID 31632196, 2019). "Through biological analysis and cytological validation, it was confirmed that circulating CCT8 is a new predictive biomarker for pancreatic cancer." (PMID 31632196, 2019). "In pancreatic cancer, CCT8 was secreted from an invasive pancreatic cancer cell line, likely through the exosome pathway, and could serve as a liquid biopsy marker to monitor the progress of cancer patients." (PMID 35602608, 2022). "Currently, the relationship between the function of CCT8 as a secreted protein and pancreatic cancer has not been reported in the literature." (PMID 31632196, 2019). "There have been no literature reports of the function of CCT8 in pancreatic cancer." (PMID 31632196, 2019).
AIDS (2 papers, 2015 to 2021). A syndrome resulting from the acquired deficiency of cellular immunity caused by the human immunodeficiency virus (HIV). "Lastly, TCP1 chaperon complex member 8 (CCT8) was found to be an important marker for disease progression towards AIDS, showing low expression during slow/non- progression, and increasing correspondingly in AIDS." (PMID 34835333, 2021).
B-cell non-Hodgkin lymphoma (2 papers, 2021 to 2024). The most common type of non-Hodgkin lymphoma. "Overexpression of CCT8 could promote the proliferation, accelerate the G1/S transition and reverse cell adhesion-mediated drug resistance (CAM-DR) phenotype in B-cell non-Hodgkin’s lymphoma." (PMID 33815471, 2021).
colon cancer (2 papers, 2020 to 2025). "And CCT8 has been reported to be upregulated in colon cancer and HCC." (PMID 33313411, 2020).
Huntington disease (2 papers, 2016 to 2021). Huntington disease (HD) is a rare neurodegenerative disorder of the central nervous system characterized by unwanted choreatic movements, behavioral and psychiatric disturbances and dementia. "Ectopic expression of CCT8 also ameliorates the age-associated demise of proteostasis and corrects proteostatic deficiencies in worm models of Huntington's disease." (PMID 27892468, 2016). "Interestingly, mimicking proteostasis of human pluripotent stem cells by ectopically increasing CCT8 in somatic tissues can suppress the aggregation of disease‐related proteins such as polyQ‐expanded huntingtin, the mutant protein underlying Huntington's disease." (PMID 34327811, 2021).
lung adenocarcinoma (2 papers, 2023 to 2025). A carcinoma that arises from the lung and is characterized by the presence of malignant glandular epithelial cells. "Therefore, CCT8 might be used as a diagnostic biomarker for the prognosis of lung adenocarcinoma." (PMID 37928427, 2023). "Survival analysis indicated that CCT8 expression is closely correlated with inferior overall survival in lung adenocarcinoma (LUAD), but not in lung squamous carcinoma (LUSC)." (PMID 37928427, 2023).
allergic disease (1 paper, 2021). An immune response that occurs following re-exposure to an innocuous antigen, and that requires the presence of existing antibodies against that antigen. "It is tempting to speculate that such a shift towards a Th1-type immune response due to an absence of regular CCT8 function may be harnessed therapeutically in non-infectious, Th2-driven pathologies (e.g. allergic diseases)." (PMID 34083746, 2021).
asthma (1 paper, 2022). "Current studies have found that CCT8 was overexpressed in cancer, but no study so far has reported any association of CCT8 with asthma." (PMID 35645813, 2022).
brain malformations (1 paper, 2025). "Recent reports provide evidence for presence of variants in several TRiC/CCT members including CCT1, CCT3, CCT5, CCT6A, CCT7 and CCT8, in brain malformations, seizures, and intellectual disability." (PMID 40779003, 2025).
developmental delay (1 paper, 2023). "The gene cct-8, a subunit of the protein folding complex TRiC, has variation that causes a putative protein coding change (G226V), which is correlated with reduced developmental delay." (PMID 37561720, 2023).
renal carcinoma (1 paper, 2022). A carcinoma arising from the epithelium of the renal parenchyma or the renal pelvis. "As indicated by this report and our work, CCT8 is a renal cancer antigen, and it was presumed to be a renal cancer-specific antigen in this paper." (PMID 36789694, 2022).
retinal degeneration (1 paper, 2019). Degeneration of the retina. "Similar to our cct5 mutant, cct1, cct2, cct3, cct4 and cct8 mutant zebrafish show retinal degeneration, suggesting that the cct5/tcf7l1a double mutant phenotype is due to abrogation of TRiC chaperonin function, a conclusion supported by cct3 knockdown in tcf7l1a mutants." (PMID 30777146, 2019).
stomach adenocarcinoma (1 paper, 2019). "The stomach adenocarcinoma dataset revealed that overall survival was significantly altered as a result of differential expression of four HSPs - CCT8, DNAJC19, GAK and SEC63." (PMID 30578123, 2019).